ATM (ATM serine/threonine kinase)
Diseases named in the same sentence as ATM in open-access papers (continued):
Sharing a sentence is not in itself a finding about the gene and the disease.
lymphoma (94 papers, 2007 to 2026). A malignant (clonal) proliferation of B- lymphocytes or T- lymphocytes which involves the lymph nodes, bone marrow and/or extranodal sites. "Single-agent activity has been observed in ATM-deficient tumors, including lymphomas; in a first-in-human study, 30% of evaluable patients achieved ≥4-month stable disease and two patients with ATM-loss cancers achieved partial responses (NCT03188965)." (PMID 41190241, 2025). "It is not possible to provide reliable estimates for individual cancers, but 9 of the 11 cancers were at sites that are also associated with ATM PTVs, including stomach, pancreas, lymphomas, and leukaemia." (PMID 40451289, 2025). "Alterations in ATM signaling and its main effectors can disrupt V(D)J process and predispose human T cells to leukemia and lymphoma." (PMID 36673351, 2023). "It is known that lymphomas arising in ATM-deficient mice display consistent cytogenetic abnormalities at the Tcr/α/δ locus." (PMID 37754262, 2023). "Given the relationship between ATM deficiency and sensitivity to DNA-PKcs inhibitors, the effects of these inhibitors on lymphoma have been investigated." (PMID 34732266, 2021). "ATM is associated with some types of leukemia and lymphoma and it has also been described in neuroblastoma with 11q deletion." (PMID 33916788, 2021). "In summary, we show that enhanced SIRT3 expression promotes lymphoma growth in an ATM deficient background." (PMID 33273545, 2020). "The mutation in ATM gene is responsible for the highly increased incidence of lymphomas and leukemia in these patients." (PMID 32850458, 2020). "Reports suggest that miR-18a-3p regulates autophagy pathways, directly targets the 3′UTR of the ataxia telangiectasia mutated (ATM) gene, and regulates DNA damaging activity in Epstein–Barr virus-associated lymphomas." (PMID 32971935, 2020). "Subsequently, we directly investigated if lymphoma growth related to ATM deficiency is a result of SIRT3 stimulation." (PMID 33273545, 2020). "Our published data support defining the role of altered sirtuin signaling in ATM-deficient lymphoma." (PMID 33273545, 2020). "Targeting SIRT3 dependent metabolic control of tumor cells in ATM deficient lymphoma patients will have clinical significance and likely lead to alternative novel therapeutic strategies in these patients." (PMID 33273545, 2020). "Based on these findings, we embarked on interrogating the role of FOXO-SIRT axis in lymphoma development in the context of ATM deficiency." (PMID 33273545, 2020). "Expression of kinase-dead ATM (AtmKD/-) is more oncogenic than loss of ATM (Atm-/-) in mouse models, leading to earlier and more frequent lymphomas with Pten deletions." (PMID 27304073, 2016). "The study also showed that the survival of the ATM-deficient lymphoma cells was dependent on NF-κB activity using pharmacological inhibitors of IKK." (PMID 27677594, 2016). "Germline inactivation of ATM causes ataxia-telangiectasia (A-T), which is associated with greatly increased risk of lymphoma and leukemia." (PMID 27304073, 2016). "Coherent with its role in checkpoint signaling and genome maintenance, ATM is frequently mutated in various human cancer entities, ranging from solid tumors to lymphomas and leukemias." (PMID 26113859, 2015).
lymphoma (continued). "Loss of ATM significantly augments Myc-induced tumorigenesis in epithelial tumor (K5-Myc) as well as lymphoma (Eμ-myc) mouse models." (PMID 24681585, 2014). "ATM deficiency leads to severe defects in many tissues and a higher incidence of lymphoma in mice probably through an elevated ROS level and an increased genomic instability." (PMID 24474198, 2014). "The first clear link between ATM and cancer consists of the observation that AT patients, among other features, display an increased predisposition to the development of lymphoma and leukaemia." (PMID 24681585, 2014). "ATM aberrations have been mainly implicated in the development of lymphomas, including T-cell prolymphocytic leukemia, mantle cell lymphoma, diffuse large B-cell lymphoma and B-cell chronic lymphocytic leukemia." (PMID 25115387, 2014). "Loss of ATM accelerates c-Myc-induced tumorigenesis in both an epithelial tumor (K5-myc) and lymphoma model (Eμ-myc) in part by reducing apoptosis and augmenting proliferation." (PMID 23532176, 2013). "For example, mutational inactivation of the “ataxia telangiectasia mutated (ATM)” gene in mice causes progressive BM failure and a high incidence of lymphoma." (PMID 22448248, 2012). "Mouse studies have shown that ATM or CHEK2 deficient mice often develop lymphoma." (PMID 40253392, 2025). "Noteworthy, ARID1A at 1p36.11 and ATM at 11q22.3 both map on significant narrow chromosome focal deletions in SS, a finding that further underlines the pathogenic role of these two genes in this lymphoma." (PMID 40918137, 2025). "Using a TERT allele under tamoxifen regulation, a model of mice with ATM mutation and susceptibility to lymphoma was created (TERT-ER), and it was found that lymphoma cells once again entered a telomere-based crisis following the cessation of telomerase activity." (PMID 38270117, 2023). "For example, inherited mutations in the ATM lead to ataxia-telangiectasia (A-T), a rare premature aging disease with features of neurodegeneration and increased risks of developing lymphomas and various solid malignancies, including breast and digestive tract cancers." (PMID 36435816, 2022). "Therefore, unraveling lymphoma-specific metabolic pathways occurring in ATM deficient background will provide critical mechanistic insights leading towards effective therapies." (PMID 33273545, 2020). "Although previous reports showed that ATM deficiency leads to mitochondrial abnormalities in normal lymphoblastoid cells and thymocytes, it is unclear how ATM deficiency affects mitochondrial structure and function in lymphoma." (PMID 33273545, 2020). "The suppression was associated with a T cell-mediated immune response in ATM(-/-)Bcl11b(+/-) mice, revealing a haploid insufficient function of Bcl11b in immune modulation against lymphoma and offering an explanation for the complex relationship between Bcl11b status with T-ALL prognosis." (PMID 26219558, 2015). "Prior evidence linking ATM with lymphoid malignancies has been largely restricted to the somatic level; ATM somatic mutations were noted in particular lymphoma subtypes of DLBCL, CLL, and MCL, consistent with the results of the subtype-specific analysis in our data." (PMID 25010664, 2014). "The reduction of ATM expression has been strongly linked with radiosensitivity and defective DNA damage-induced ATM-dependent signaling in various experimental studies, and was clearly shown to promote the tumor growth in lymphoma and other cancer models." (PMID 25010664, 2014).
lymphoma (continued). "The next-generation sequencing performed on the sample confirms that the predominant T-cell clones in this lymphoma contained CAR-T cell fusion mRNA, with potential driver mutations found in TET2, BRAF (V600E), PPM1D, ATM, and RUNX1." (PMID 41509667, 2026). "Two women carrying recurrent mutations in BRCA2 (c.1763_1766delATAA, p.Asn588Serfs*25) and ATM (c.5496 + 2_5496 + 5delTAAG) genes had the diagnosis of other types of cancer that is, lymphoma and, thyroid and gastric, respectively." (PMID 38890714, 2024). "To evaluate the anti-lymphoma efficacy of the combination treatment in vivo, we choose a CDX model derived from ATM-deficient Granta-519 and treated the mice with inhibitors of PRMT5, and ATR, alone or together." (PMID 36797243, 2023). "The findings revealed a significant difference in disease-free survival (DFS) between patients with lymphoma with ATM deletion and those with a normal ATM gene expression (p < 0.001)." (PMID 37283790, 2023). "This is also consistent with the observations that lymphomas, which has the higher frequency of ATM deletions, display better response to DNA-PK inhibitors." (PMID 37663435, 2023). "Levels of the checkpoint kinase CHK2, which functions downstream of ATM in response to double strand DNA breaks, appeared broadly comparable, albeit variable, in the untreated Eμ-Myc WT and Eμ-Myc/cRel−/− lymphoma cells." (PMID 36240066, 2022). "An example supporting this idea is that B cell–specific inactivation of ATM (one of the traits in our study) synergizes with ectopic cyclin D1 expression to promote pregerminal center lymphoma in mice." (PMID 34882582, 2022). "KU-60019 (KU-55933 analog) is a potent and selective inhibitor of ATM, which has been used in the treatment of solid tumors, as well as leukemia and lymphoma." (PMID 34732266, 2021). "To determine if SIRT3 assists DLBCL cells to resists metabolic stress, we first determined expression of SIRT1, SIRT3 and ATM in human lymphoma samples to understand clinical relevance of these markers in DLBCL." (PMID 33273545, 2020). "Given that ATM is mutated or lost in over 40% of MCL, we and others examined the effects of ATM loss on PARP inhibitor sensitivity in human lymphoma cell lines that lack ATM protein expression." (PMID 32183301, 2020).
lymphoma (continued). "Our data illustrates the clinical significance of targeting addiction to SIRT3 influenced metabolic pathways in order to impede lymphoma growth in presence of low ATM expression." (PMID 33273545, 2020). "Western analysis of PARP and phosphorylated H2AX expression levels in one representative cell line for each lymphoma subtype confirmed that addition of the ATM inhibitor to romidepsin increases the apoptotic effects of the HDACi." (PMID 32973968, 2020). "Doxorubicin-induced DNA damage was significantly increased in lymphoma cell lines exposed to a Pim kinase inhibitor, in association with significant downregulation of the DNA DSB response proteins H2AX, ATM and Chk2." (PMID 27374090, 2016). "ATM-deficient (ATM−/−) mice exhibit hematopoietic stem cell (HSC) dysfunction and a high incidence of lymphoma." (PMID 24474198, 2014). "The rare syndromes attributed to inherited mutations in DNA repair genes, such as ataxia talangiectasia (A-T; mutations in ATM) or Nijmegen breakage syndrome (NBS; mutations in NBS1) manifest with early onset lymphomas of various histological subtypes." (PMID 25010664, 2014). "As A-T patients are prone to lymphomas, it is likely that the ability of ATM to monitor the development of lymphocytes through the regulation of both DNA repair and apoptosis plays a critical role in tumor suppression." (PMID 23532176, 2013). "There is a growing evidence that oral poly (ADP-ribose) polymerase inhibitor, olaparib impedes the growth of ATM null or ATM mutant lymphoma cells in vitro and in vivo by instigating the accumulation of intolerable levels of DNA damage in cycling tumor cells." (PMID 22485171, 2012). "While it would be difficult to reconcile all the differences in relation to the interaction between LMP1 and ATM, it did indicate a complex regulatory network in different cancers, in this case, lymphomas and NPCs." (PMID 22096476, 2011). "Ongoing studies focus on ATM-mutant chronic lymphocytic leukemia, lymphomas, and solid tumors." (PMID 41190241, 2025). "Moreover, although Casp2−/− mice do not develop tumors spontaneously, loss of Casp2 promotes tumorigenesis in many mouse models including Eμ-Myc lymphoma, c-Neu-driven mammary carcinoma, and ATM−/− lymphoma." (PMID 38676703, 2024). "Previous studies have demonstrated that cells with defective ATM function exhibit heightened radiosensitivity, which may be advantageous for treating highly chemo resistant lymphoma subtypes with radiotherapy." (PMID 37283790, 2023). "We also analysed the phosphoproteomic dataset from Eμ-Myc Rel−/− lymphomas for evidence of any general changes in ATR, Ataxia Telangiectasia Mutated (ATM) or DNA-Dependent Protein Kinase (DNA-PK, PRKDC) dependent phosphorylation, whose target phosphosites generally contain an SQ or TQ motif." (PMID 36240066, 2022).
lymphoma (continued). "We know that germline mutations, mostly deletions, that lead to the complete absence of ATM protein in A-T syndrome are associated with greatly increased risk of lymphoma and leukemia." (PMID 34771661, 2021). "While some of the affected genes such as ATM, CCND1, and KMT2D are known to be mutated in MCL, a large subset has not been reported as mutated before in this lymphoma but mutated in other types of lymphoma, as detailed in the Results section." (PMID 31334109, 2019). "Mice lacking ATM exhibit growth retardation, early lymphomas, and pleiotropic phenotypes associated with human ATM deficiency." (PMID 29909278, 2018). "While our data demonstrate that non-canonical ATM activation was normal in human ASCIZ/ATMIN-knockout lymphoma cells, we acknowledge that reduced ATM activation in response to aphidicolin treatment has recently been reported in human ASCIZ/ATMIN siRNA knockdown cell lines." (PMID 28648892, 2017). "However, in lymphoma cells APOBEC3G has been shown to enter the nuclear compartment as part of a DNA damage response and promote DNA repair by activating the ataxia telangiectasia mutated (ATM) DNA damage checkpoint kinase." (PMID 27634334, 2016). "Furthermore, the authors employed a murine xenograft model of an ATM-mutant mantle cell lymphoma cell line to demonstrate a significantly reduced lymphoma burden and an increased survival of animals following olaparib treatment in vivo." (PMID 26113859, 2015). "Interestingly, the ATM−/− Gadd45a−/− mice showed higher a incidence of lymphoma and leukemia, as well as an increased rate of metastasis compared to ATM−/− mice." (PMID 24474198, 2014). "Furthermore, we also observed an increased metastasis (one case of BM infiltration and one case of spleen infiltration) in ATM−/− Gadd45a−/− mice, which indicates that Gadd45a deletion increases the degree of malignancy of lymphoma in ATM−/− mice." (PMID 24474198, 2014). "Previous study showed a high incidence of lymphoma in ATM−/− mice." (PMID 24474198, 2014). "A role for Suv39h1 in preventing Ras-induced lymphoma development in vivo has already been demonstrated, supporting the concept that Suv39h1/2-mediated regulation of ATM activity in a hypoxic context could halt tumorigenesis in response to oncogenic stress." (PMID 24268576, 2013). "One woman was diagnosed with lymphoma with a prior ductal BC, and she had a heterozygous BRCA2 c.1763_1766delATAA, p.Asn588Serfs*25; the other one had three cancers, thyroid, gastric, and ductal BC harboring an ATM c.5496 + 2_5496 + 5delTAAG, a likely pathogenic mutation." (PMID 38890714, 2024). "However, the appearance of these tumors was somewhat delayed, and lymphomas did not exhibit the Tcr/α/δ rearrangement typical of ATM deficiency." (PMID 37754262, 2023). "The analysis of twenty cases of MCL tumor revealed a significantly higher number of chromosomal imbalances in typical MCL with ATM gene alterations than in tumors with wild-type ATM, suggesting that ATM inactivation may favor increasing chromosomal instability in these lymphomas." (PMID 34771661, 2021). "Hence, there is a need for therapeutic strategies that act independent of DDR that can target ATM deficient lymphoma and other related B-cell malignancies in ATM deficient background." (PMID 33273545, 2020). "Finally, shRNA knockdown of mutated ATM in Granta519 human lymphomas cell lines, moderately, yet significantly, rescued the CPT hypersensitivity and CPT induced apoptosis associated with the expression of catalytically inactive ATM." (PMID 27304073, 2016).